CYP3A43 (cytochrome P450 family 3 subfamily A member 43)
Description:
Exhibits low testosterone 6-beta-hydroxylase activity in vitro. The physiological substrate of this enzyme is unknown.
Tractability: Small molecule: an approved drug acts on it; it belongs to a druggable protein family. Antibody: UniProt places it where antibodies can reach, with medium confidence. PROTAC: a small molecule that binds it is known.
Target class: Enzyme; Oxidoreductase
Gene: Protein-coding gene on chromosome 7 (99,827,922 to 99,867,305, forward strand). Ensembl gene ENSG00000021461.
Subcellular location: Endoplasmic reticulum membrane; Microsome membrane
Subcellular location (Human Protein Atlas): Cytosol; Vesicles
Pathways (Reactome):
Metabolism: Miscellaneous substrates; Xenobiotics
Gene Ontology:
Molecular function: estrogen 16-alpha-hydroxylase activity; monooxygenase activity; testosterone 6-beta-hydroxylase activity; heme binding; iron ion binding; oxidoreductase activity, acting on paired donors, with incorporation or reduction of molecular oxygen; oxidoreductase activity, acting on paired donors, with incorporation or reduction of molecular oxygen, reduced flavin or flavoprotein as one donor, and incorporation of one atom of oxygen
Biological process: cytochrome metabolic process; oxidative demethylation; steroid metabolic process
Cellular component: endoplasmic reticulum membrane
Genetic constraint (gnomAD): Loss-of-function variants: 41 observed, 55.6 expected, observed/expected ratio (o/e) 0.74, 90% interval 0.57 to 0.96. The upper end of that interval is the gene's LOEUF score, 0.96, which puts it in group 4 of 6, group 1 being the genes least tolerant of losing a copy. Missense variants: 542 observed, 581 expected, observed/expected ratio (o/e) 0.93, 90% interval 0.87 to 1. Synonymous variants: 178 observed, 198.28 expected, observed/expected ratio (o/e) 0.9, 90% interval 0.79 to 1.02.
Homologues: Orthologues: chimpanzee CYP3A43 (99% identical), macaque CYP3A43 (96% identical), dog CYP3A26 (74% identical), dog CYP3A12 (73% identical), dog CYP3A26 (71% identical), rat Cyp3a9 (68% identical), mouse Cyp3a13 (67% identical), pig CYP3A29 (67% identical), mouse Cyp3a25 (66% identical), mouse Cyp3a57 (65% identical), rat Cyp3a62 (65% identical), mouse Cyp3a11 (65% identical), and 19 more. Paralogues in human: CYP3A4 (76% identical), CYP3A5 (76% identical), CYP3A7 (71% identical).
Diseases named in the same sentence as CYP3A43 in open-access papers:
CYP3A43 is named in the same sentence as 18 diseases in open-access papers, as found by Europe PMC text mining. Sharing a sentence is not in itself a finding about the gene and the disease. The quoted sentences say what the papers report.
breast carcinoma (4 papers, 2012 to 2025). "CYP3A43 polymorphisms, meanwhile, have been identified as potential biomarkers for breast cancer prognosis." (PMID 41300329, 2025). "A study on CYP3A43 polymorphisms in breast cancer showed a significant association between CYP3A43_74_delA (CYP3A43*2A, rs61469810) and tumor grade." (PMID 36613552, 2022). "The CYP genes with the lowest expression in the TCGA breast cancer cohort were: CYP1A2 (0.010), CYP3A43 (0.029), CYP3A7 (0.033), CYP2C9 (0.044) and CYP3A4 (0.044)." (PMID 28684774, 2017).
Infertility (2 papers, 2024 to 2025). "Although there was evidence for distinct genetic architectures of infertility and reproductive hormones, we showed that individual genes containing rare protein-coding variants associated with testosterone (GPC2, CYP3A43 and TRIM4) were also associated with higher risk of infertility in the UKBB." (PMID 40229599, 2025). "Although there was evidence for distinct genetic architectures of infertility and reproductive hormones, we showed that individual genes containing rare protein-coding variants associated with testosterone (GPC2, CYP3A43, TRIM4) were also associated with higher risk of infertility in the UK Biobank." (PMID 38562841, 2024).
lung carcinoma (2 papers, 2022 to 2023). "CYP3A43 depletion promoted the proliferation and migration of lung cancer cells and enhanced xenograft lung cancer growth." (PMID 38001897, 2023). "We first compared the mRNA and protein expression level of CYP3A43 in different human lung cancer cell lines to that in BEAS-2B cells." (PMID 36613552, 2022). "We report, for the first time to our knowledge, the unprecedented biological functions of CYP3A43 in suppressing the proliferation and migration of human lung cancer cells both in vitro and in vivo." (PMID 36613552, 2022).
ovarian carcinoma (2 papers, 2022 to 2023). A malignant neoplasm originating from the surface ovarian epithelium. "Bioinformatic studies have demonstrated the association of CYP3A43 with liver cancer and ovarian cancer." (PMID 36613552, 2022). "In contrast, high mRNA expression of CYP2A6, CYP2C9, CYP2J2, CYP3A4, CYP3A5, CYP3A7, and CYP3A43 connoted a good prognosis for ovarian cancer patients." (PMID 38001897, 2023). "Significant differences in the intensity of CYP3A43 protein expression between primary ovarian cancer and normal ovary samples were of particular interest." (PMID 38001897, 2023). "Another study reported that CYP3A43 expression in ovarian cancer was higher than its expression in the normal ovary, but CYP3A43 was not identified as an independent prognostic marker of ovarian cancer." (PMID 36613552, 2022).
prostate carcinoma (2 papers, 2022). A carcinoma that arises from epithelial cells of the prostate gland. "Several CYP enzymes, including CYP3A43, can be considered prognostic and diagnostic markers of prostate cancer." (PMID 36359206, 2022). "Another polymorphic gene variant (CYP3A43*3) contains the SNP rs680055 and codes for a mutated enzyme (CYP3A43:p.Pro340Ala), which is associated with an elevated risk for prostate cancer and also with increased mortality." (PMID 36551778, 2022). "Androgen receptor-regulated signaling pathways play a key role in the progression of the prostate cancer in which androgen-metabolizing enzymes CYP3A4, CYP3A5, and CYP3A43 are expressed." (PMID 36359206, 2022).
acute coronary syndrome (1 paper, 2021). Signs and symptoms related to acute ischemia of the myocardium secondary to coronary artery disease. "Two variants on CYP3A43 were identified to be associated with Ticagrelor levels in individuals with acute coronary syndromes treated with ticagrelor and serum metabolite measurement respectively." (PMID 34863089, 2021).
breast tumors (1 paper, 2012). "One study reported an association between the rs61469810 polymorphism of CYP3A43 (CYP3A43*2A) and poorly differentiated breast tumors which may be explained by a potential contribution of the variant allele to increased sex hormone levels." (PMID 23226154, 2012).
diabetes (1 paper, 2021). "Although the direct relationship between CYP3A43 and diabetes/obesity was not well known, some variants located in CYP3A4 have been identified in previous studies to be associated with relevant metabolism traits." (PMID 34863089, 2021).
epilepsy (1 paper, 2017). A brain disorder characterized by episodes of abnormally increased neuronal discharge resulting in transient episodes of sensory or motor neurological dysfunction, or psychic dysfunction. "Among the top ten hyper- and top ten hypo-methylated genes, a subset (i.e., GABRB1, LC34A2, CLCN6, CLCA4, CYP3A43, CYP3A4, CYP2C9) has been related to epilepsy in epidemiological, pathophysiological or clinical context (to be discussed further)." (PMID 28276448, 2017).
hepatocellular carcinoma (1 paper, 2022). A malignant tumor that arises from hepatocytes. "One study reported that CYP3A43 may be a promising predictive marker for hepatocellular carcinoma, as low expression level of CYP3A43 in tumor tissues was associated with reduced median survival of patients." (PMID 36613552, 2022).
lung adenocarcinoma (1 paper, 2022). A carcinoma that arises from the lung and is characterized by the presence of malignant glandular epithelial cells. "To further reveal the role of CYP3A43 in tumor progression, we first analyzed the data from the UALCAN database and found that CYP3A43 was negatively correlated to the cancer staging and lymph node metastasis of lung adenocarcinoma (LUAD)." (PMID 36613552, 2022).
lymph node metastasis (1 paper, 2022). "In our analysis, CYP3A43 expression was negatively associated with the clinical stage and lymph node metastasis of LUAD patients." (PMID 36613552, 2022). "In summary, the current study showed that CYP3A43 expression was negatively correlated with the clinical stage and lymph node metastasis of LUAD patients." (PMID 36613552, 2022). "We found a correlation between the expression level of CYP3A43 and the cancer staging and lymph node metastasis." (PMID 36613552, 2022).
metastatic tumors (1 paper, 2024). "Of the many APUC genes that have been associated with the activation of AR, we found that 6 (HSD3B1, HSD3B2, CYP11A1, CYP11B1, CYP17A1, and CYP3A43) exhibit robust association in prostate and metastatic tumors and were mutually exclusive with heightened AR activity." (PMID 39207857, 2024). "Six APUC genes (HSD3B1, HSD3B2, CYP3A43, CYP11A1, CYP11B1, CYP17A1) exhibited coalescent gene behavior in a cohort of metastatic tumors (n = 208)." (PMID 39207857, 2024).
cancer (5 papers, 2015 to 2024). A tumor composed of atypical neoplastic, often pleomorphic cells that invade other tissues. "Specifically, CYP3A43 levels in cancer samples from stage 3 patients were significantly lower than those in samples from stage 1 (p = 0.003) and stage 2 patients (p = 0.02), respectively." (PMID 36613552, 2022). "Based on the observation that CYP3A43 knockdown promotes the proliferation and migration of H1299 cells, we suspect that CYP3A43 overexpression could block and inhibit cancer." (PMID 36613552, 2022). "The dual role of CYP3A43 indicates that it may participate in the development of cancer and that its function is tissue specific." (PMID 36613552, 2022). "However, the biological function of CYP3A43 in cancer is scarcely explored." (PMID 36613552, 2022). "Altogether, HSD3B1, HSD3B2, CYP11A1, CYP11B1, CYP17A1, and CYP3A43, hereby defined as APUC-6, demonstrated tissue- and cancer stage–specific interactions, with the most notable interaction in metastatic PC." (PMID 39207857, 2024). "As increased cellular proliferation and migration are the hallmarks of cancer cells, the observation that CYP3A43 knockdown promotes proliferation and migration of H1299 cells provides evidence to address how CYP3A43 negatively affects LUAD patients’ cancer stage and lymph node metastasis." (PMID 36613552, 2022).
tumor (5 papers, 2015 to 2025). "The CYP3A43 gene (7q22.1) is affected by a point mutation in all tumor steps and in addition LOH in the asynchronous metastasis." (PMID 25730902, 2015). "As we examined tumor sites within the 22 adrenal metastasis samples, it was clear that HSD3B1 and CYP3A43 exhibited robust association with AR expression (R = 0.7 and 0.56), whereas the rest of the APUC-6 genes did not." (PMID 39207857, 2024). "Our in vivo experimental results demonstrated that CYP3A43 knockdown also significantly accelerates tumor growth." (PMID 36613552, 2022). "We further investigated the function of CYP3A43 on tumor growth in vivo using a xenograft mouse model." (PMID 36613552, 2022). "We found that CYP3A43 knockdown accelerated tumor growth and increased tumor weight." (PMID 36613552, 2022). "CYP3A43 knockdown also significantly promoted tumor growth in a xenograft mouse model." (PMID 36613552, 2022). "Key predictors included clinical variables (age, tumor size, NPI, radiotherapy) and molecular markers (ATM, HERC2, AKT2, FOXO3, CYP3A43)." (PMID 41300329, 2025). "Feature selection was performed using the Boruta algorithm, which revealed that both clinical parameters (e.g., age, tumor size, NPI, radiotherapy) and transcriptomic biomarkers (e.g., ATM, HERC2, AKT2, CYP3A43, FOXO3) provided strong prognostic contributions." (PMID 41300329, 2025). "However, the biological function of CYP3A43 in tumor progression remains unclear." (PMID 36613552, 2022). "We established stable CYP3A43-knockdown LUAD H1299 cell line and found that its knockdown enhanced cell proliferation, colony formation, and migration in vitro, and promoted the growth of tumor xenograft in vivo." (PMID 36613552, 2022). "Furthermore, decreased CYP3A43 expression was observed in tumor tissues with lymph node metastasis (p = 0.03) compared to tumor tissues without lymph node metastasis." (PMID 36613552, 2022).
CYP3A43 also shares sentences with these, for which no sentence is quoted: liver cancer (1 paper); nephrotic syndrome (1); Obesity (1).